PCDHA13 (protocadherin alpha 13)
Description:
Potential calcium-dependent cell-adhesion protein. May be involved in the establishment and maintenance of specific neuronal connections in the brain.
Synonyms: CNRS5; CNR5; CRNR5; CNRN5; PCDH-ALPHA13
Tractability: Antibody: UniProt places it where antibodies can reach, with medium confidence; UniProt predicts a signal peptide or a membrane-spanning region; its Gene Ontology location is reachable by antibodies, with medium confidence.
Gene: Protein-coding gene on chromosome 5 (140,882,124 to 141,012,347, forward strand). Ensembl gene ENSG00000239389.
Subcellular location: Cell membrane
Gene Ontology:
Molecular function: cell adhesion molecule binding; calcium ion binding
Biological process: cell adhesion; homophilic cell-cell adhesion; nervous system development
Cellular component: plasma membrane; membrane
Genetic constraint (gnomAD): Loss-of-function variants: 54 observed, 67.65 expected, observed/expected ratio (o/e) 0.8, 90% interval 0.64 to 1. The upper end of that interval is the gene's LOEUF score, 1, which puts it in group 4 of 6, group 1 being the genes least tolerant of losing a copy. Missense variants: 1,248 observed, 1,328.4 expected, observed/expected ratio (o/e) 0.94, 90% interval 0.9 to 0.98. Synonymous variants: 587 observed, 607.5 expected, observed/expected ratio (o/e) 0.97, 90% interval 0.9 to 1.03.
Homologues: Orthologues: mouse Pcdha12 (87% identical), pig PCDHA13 (68% identical). Paralogues in human: PCDHA4 (82% identical), PCDHA3 (82% identical), PCDHA2 (82% identical), PCDHA1 (81% identical), PCDHA9 (81% identical), PCDHA8 (81% identical), PCDHA7 (81% identical), PCDHA6 (81% identical), PCDHA11 (81% identical), PCDHA12 (80% identical), PCDHA5 (80% identical), PCDHA10 (80% identical), and 49 more.
Diseases named in the same sentence as PCDHA13 in open-access papers:
PCDHA13 is named in the same sentence as 10 diseases in open-access papers, as found by Europe PMC text mining. Sharing a sentence is not in itself a finding about the gene and the disease. The quoted sentences say what the papers report.
Alzheimer disease (2 papers, 2024). A progressive, neurodegenerative disease characterized by loss of function and death of nerve cells in several areas of the brain leading to loss of cognitive function such as memory and language. "Many of these genes have been previously linked to brain-related disorders, including Alzheimer’s disease (WDR12, AGFG2, and CDK5RAP3), schizophrenia (SRA1, WDR55, CORO7, DDAH2, PCDHA8), autism spectrum disorder (MAPK3, PCDHA13), and major depressive disorder (ZMAT2 and ITIH4)." (PMID 39269986, 2024).
cervical cancer (2 papers, 2015 to 2023). A primary or metastatic malignant neoplasm involving the cervix. "Comparing to high-risk HPV test, methylated PCDHA4 and PCDHA13 were as frequently found in invasive cervical cancer but was much less frequently found in normal or CIN1." (PMID 25418975, 2015).
depression (2 papers, 2024). "The overlapping eQTL genes between AD and depression (SRA1, MICA, PCDHA8, PCDHA10, PCDHA7, and PCDHA13), were not yet associated with these disorders through proximity analysis nor have an established role in these diseases as of yet." (PMID 38862462, 2024).
glioma (1 paper, 2011). A benign or malignant brain and spinal cord tumor that arises from glial cells (astrocytes, oligodendrocytes, ependymal cells). "Eight promoter-hypermethylated genes (ANKDD1A, GAD1, HIST1H3E, PCDHA8, PCDHA13, PHOX2B, SIX3, and SST) were confirmed in primary glioma and cell lines." (PMID 21962230, 2011). "The methylation levels in the PCDHA13 promoter in primary glioma samples, but not in glioma cell lines, were also significantly higher than that in non-tumor controls (p < 0.01)." (PMID 21962230, 2011). "The GAD1, HIST1H3E, PCDHA8, PCDHA13, SIX3 and SST may regulate the progression of glioma." (PMID 21962230, 2011). "In addition, we found that the percentages of promoter methylation in the ANKDD1A and PHOX2B, but not the GAD1, HIST1H3E, PCDHA8, PCDHA13, SIX3 and SST, were associated negatively with the differentiation degrees of human gliomas." (PMID 21962230, 2011).
cancer (2 papers, 2015 to 2016). A tumor composed of atypical neoplastic, often pleomorphic cells that invade other tissues. "The study also reported that there was a positive correlation between methylation frequency of PCDHA4 and PCDHA13 and tumor severity, highlighting the role of PCDHA4 silencing in cancer progression." (PMID 27842508, 2016).
PCDHA13 also shares sentences with these, for which no sentence is quoted: tumor (2 papers); autism spectrum disorder (1); cytomegalovirus infection (1); kidney tumor (1); schizophrenia (1).